IL2 (interleukin 2)
Diseases named in the same sentence as IL2 in open-access papers (continued):
Sharing a sentence is not in itself a finding about the gene and the disease.
cancer (continued). "In addition, deletion of Smad3 also enhanced the anticancer activities of NK cells by increasing the levels of granzyme B, interleukin (IL)-2 and IFN-γ locally within the cancer microenvironment and in the systemic circulation." (PMID 28262747, 2017). "Additionally, under circumstances of strong CD8+ T cell priming, e.g. in cancer-vaccine settings, Tregs by regulating IL-2 homeostasis, limit CD8+ T cell responsiveness to IL-2 thereby preventing their expansion and survival." (PMID 29037250, 2017). "Turbitt suggested that it is possible that n-3 PUFAs induced an increase in IL-2 and IFN-g production in T cells, which may drive a Th1 response, enhance antitumor immunity, and contribute to the cancer prevention effect of n-3 PUFAs." (PMID 28410575, 2017). "In conclusion, we confirmed that just as morphine, ketamine dose-dependently suppressed IL-2 and IFN-γ of activated T lymphocyte of patients with refractory cancer pain in vitro, but the inhibitory action of low dose ketamine could be neglected." (PMID 28422864, 2017). "IL2 is the only one approved by the Food and Drug Administration (FDA) for the treatment of cancer." (PMID 27736965, 2016). "Regarding the cytokines evaluated in the serum of individuals with and without cancer, significant differences were observed among individuals with cancer for IL2, IL10, TNF-α, IFN-g and IL17." (PMID 26905729, 2016). "It is well known that IL-2 is an important regulator for NK cell activation, and TGF-β, IDO, and IL-10 are crucial inflammatory mediators for the direct or indirect inhibition of NK cells and the initiation and progression of cancers." (PMID 27034590, 2016). "The Th1 cytokines IL-2 and IFN-Υ enhance CTL-and NK cell-mediated regression of cancer cells." (PMID 27777963, 2016). "IL-2 can have serious side effects and is used at present for cancers that do not respond to targeted therapies." (PMID 27974927, 2016). "Both IL-2/anti-IL-2 and IL-15/IL-15RαFc complexes have been shown to boost NK cell and memory CD8+ T cell numbers in mice and to enhance their cytolytic capacity against viral-infected and cancer cells." (PMID 27391012, 2016). "IL-2 has been approved by the Food and Drug Administration (FDA) for the treatment of cancers." (PMID 26754564, 2016). "IL-2 is also known to play a role in enhancing NK cell cytotoxicity and ADCC against cancer cells." (PMID 25287778, 2015). "However, IL-2 administration has been shown to alter the homeostasis and increase the amount of CD4+CD25hiFoxp3+ regulatory T cells (T regs) in cancer patients dampening the desired response." (PMID 25972868, 2015). "High level of IFN-γ was produced by NK(IL-2) cells in a co culture with cancer cells with or without ω-3 and anti-oxidants or RvD1." (PMID 26052286, 2015). "The inverse relationship between anti-SEA/E-120 antibody concentration in plasma and IL-2 production was also shown for the whole study (ASCO annual meeting 2013 abstract ID 3073, European Cancer Congress (ECCO) 2013 abstract ID 2710 and manuscript submitted for publication)." (PMID 25669986, 2015). "IL-2 therapy, although one of the oldest successes of cancer immunotherapy, to date, is still not widely implemented due to substantial associated toxicity." (PMID 24884532, 2014). "At day 14 post-infection, the frequencies of IFN-γ and IL-2 producing cells in the antigen-specific CD8+Thy1.1+ T cell compartment were not statistically different in cancer mice vs. non-cancer controls." (PMID 24796533, 2014).
cancer (continued). "The synergistic effect of combined IL-2 and IL-12 in promoting cytotoxic activity of NK cells through IFN-γ production, has been translated into a clinical therapeutic role for IL-12 in augmenting NK cytotoxity in cancer." (PMID 23957956, 2013). "IL-2, released from T helper-1 lymphocytes, induces the evolution of natural killer cells into LAK cells, which are able to exert an antigen-independent cancer cell destruction." (PMID 21654973, 2011). "Treatment with GL tended to increase mitogenic reactivity to phytohemagglutinin, counts of CD3, CD4, CD8 and CD56 lymphocytes, plasma concentrations of interleukin (IL)-2, IL-6 and interferon (IFN)-γ, and NK activity, whereas plasma concentrations of IL-1 and TNF-α were decreased in cancer patients." (PMID 19617199, 2011). "The expansion of immune effector cells in response to a combination of IFN-γ, TG and IL-2 occurred in the absence of a significant induction of Treg cells, whose infusion into cancer-bearing patients would be highly undesirable." (PMID 21138560, 2010). "Cancer immunotherapy underwent considerable progress in recent years, since the first promising results of adjuvant immune stimulation using interferon-α (IFN-α) and interleukin-2 (IL-2)." (PMID 20498710, 2010). "The first generation of ACT utilized lymphokine-activated killer (LAK) cells with high-dose IL-2 for the treatment of patients with advanced cancer but was not shown to be superior to the treatment of IL-2 alone." (PMID 21234353, 2010). "Thus, immunomodulatory cytokines including IL-2, IL-12, or IL-21 would be effective adjuvants in the enhancement of impaired ADCC in patients with cancer." (PMID 20029417, 2010). "Both interleukin-2 (IL2) and interleukin-15 (IL15) have been used for cancer immunotherapy." (PMID 19422685, 2009). "Indeed, our group has developed fully human fusion proteins based on the pro-inflammatory cytokines IL2 and TNF (L19-IL2; L19-TNF; F16-IL2) which are currently being investigated in phase I and in phase II clinical trials in patients with cancer." (PMID 19781067, 2009). "In vitro, a direct antiproliferative effect on renal tumour cells has been demonstrated for IFN-α, whereas IL-2 has no direct impact on cancer cells." (PMID 14760375, 2004). "IL-2 has no direct impact on cancer cells, which can grow unimpeded in vitro in high concentrations of IL-2." (PMID 14760375, 2004). "Antibodies to IL-2 failed to inhibit proliferation of carcinoma cells, but antibodies specific for the ligand-binding site of the IL-2R were growth inhibitory." (PMID 10555752, 1999). "In the blood cell cultures of all four groups of cancer patients, significantly lower values of IFN-gamma (P < or = 0.001), IL-2 (P < or = 0.01) and IL-1 alpha (P < or = 0.01) were found as compared to the controls, although lymphocyte and monocyte counts were almost identical." (PMID 8318418, 1993). "Under normal physiological conditions, IL-2 binds to the high-affinity IL-2 receptor on T cells to promote their proliferation and differentiation, particularly into CD8+ cytotoxic T cells and regulatory T cells, which help carry out the immune response and target cancer cells." (PMID 40699676, 2025). "Furthermore, the levels of multiple cytokines, including IL-2, IL-4, IL-6, IL-10, TNF, and IFN-γ in the supernatant of the OHSV2-DSTEFAP5/CD3 group co-cultured with cancer cells and fibroblasts, showed a significant increase compared to groups with either cell type alone." (PMID 40406146, 2025). "We anticipate that the developed tool may be of great use to the scientific community for identifying IL-2 inducing/non-IL-2 inducing peptides from the proteomes for improving the current cancer immunotherapeutics." (PMID 40670434, 2025). "Long-term co-culture in hypoxia may introduce bias due to factors such as differences in media composition, differential nutrient consumption by carcinoma cells, or absence of exogenous IL-2." (PMID 40427042, 2025).
cancer (continued). "However, administration of IL-2 adversely impacted host survival in the hu-PBMC-MHC I/II mice due to increased induction of graft versus host disease, which would pose a potential issue in the use of our TPV/Δ66R/mIL-2 recombinant during cancer studies." (PMID 38787254, 2024). "When we believe that immunotherapy could be a panacea in cancer care, we combine anti-PD1/L1 with another CPI (such as anti-CTLA-4, anti-IDO1, anti-TIGIT) and with agents that target immune factors (e.g., IL-2) and effectors (e.g., dendritic cells, T cells, macrophages, NK cells), etc." (PMID 38539487, 2024). "Enhanced levels of intracellular cytokines, such as interleukin 2(IL2), TNF-α, interferon-gamma (IFN-γ), and IL6, were observed within the memory subpopulation, indicating that IL7 may stimulate a memory immune response targeting cancer." (PMID 38289597, 2024). "In parallel with considerable overproduction of other pro-inflammatory modulators, such as TNFα, IL-2, IL-6, MIG (CXCL9), MIP-1β (CCL4) and MIP-2 (CXCL2), we also detected a significantly lower secretion of IL-10 by tILC2s that contradicted the conventional ILC2 role in cancer." (PMID 38524132, 2024). "In the early stages of cancer, M1 TAMs are present, participating in the inflammatory response and expressing many pro-inflammatory cytokines such as tumor necrosis factor (TNF)-α, interleukin-2 (IL-2), IL-6, IL-12, IL-23, nitric oxide (NO) and reactive oxygen species (ROS)." (PMID 39682696, 2024). "Also, the expression of effector T cell activation markers (IL-2, GZMB, IFNG) in edT cells were significantly lower after co-culture with T cell-resistant (R) as compared to -sensitive (S) cancer cells, indicating decreased T cell effector functionality and thus impaired PDAC cell killing." (PMID 38654067, 2024). "While IL-2 is an approved cancer immunotherapy, IL-15 has not yet established clinical benefit." (PMID 38887559, 2024). "IL-2, commonly referred to as T cell growth factor, aids in the proliferation and mobilization of body leucocytes (including natural killer T cells (NKT) and NK cells) against cancer and also aids the B cells in generating substances capable of killing cancer cells." (PMID 39483536, 2024). "However, there are still critical challenges in the therapeutic targeting of IL-2 and IL-2R in cancer, such as the lack of specificity of these molecules and the potential for side effects." (PMID 37516849, 2023). "Importantly, we found that SS at the same concentrations active in cancer cells did not affect Notch1 cleavage or expression in activated T-cells, nor did it inhibit T-cell proliferation or IL-2 secretion." (PMID 37901240, 2023). "Moreover, the long-term IL-2 expression did not impair immune responses to infections, vaccination or cancer." (PMID 37741949, 2023). "Hence, an earlier review highlighted that RBAC could be an adjuvant to cancer treatment, with RBAC working synergistically with IL-2, NKC, and chemotherapeutic agents to overcome the dysregulated apoptosis associated with excess oxidative stress in malignancy." (PMID 37651416, 2023). "However, to maximise the therapy, nowadays, IL-2 is not administered alone but in combination with other anti-cancer immunotherapies." (PMID 36631633, 2023). "Indeed, treatments with PEGylated IL‐2, NKTR‐214 (developed by Nektar therapeutics) increased cytotoxic immune cell populations, including CD8+T and NK cells, with a limited effect on Treg cell expansion in both cancer patients and preclinical models." (PMID 36684086, 2023). "Whereas unwanted activation and expansion of CD25+ regulatory T cells (Tregs) has limited many IL-2 based immunotherapies, Neo-2/15 is CD25-independent and is thus not biased to preferentially activate CD25+ Tregs22, which is one of its main advantages as a cancer therapeutic over IL-2." (PMID 36316485, 2023).
cancer (continued). "When co-culturing the transfected Jurkat cells with MM418 cells the reduction in IL-2 production seen with the GFP transfected cells was significantly attenuated by transfection of ∆Ex3PD1 vector, indicating that ∆Ex3PD1 is capable of reducing T cell exhaustion by cancer cells." (PMID 37973660, 2023). "Furthermore, IL-2 was preferentially enhanced by PD-1 blockade, and this enhancement of T cell function correlated with the IRC assay known to predict outcomes in patients with cancer." (PMID 38055623, 2023). "In the presence of cancer patients’ monocytes, the cytotoxic function was suppressed both in autologous and allogeneic healthy NK cells when they were treated with IL-2 alone, or with IL-2 + anti-CD16 mAbs, or with IL-2 + sAJ2 when compared to that of NK cells in the absence of monocytes." (PMID 35203349, 2022). "In contrast, there was a highly significant reduction in the proportion of cancer patients mounting T‐cell responses following the first dose (p < 0·0001), whereby only 27 of 56 (48·2%) and 32 of 55 (58·2%) cancer patients mounted an IFN‐γ or IL‐2 response, respectively." (PMID 34775604, 2022). "The low rate of clinical responses to combining cancer vaccines with IL-2, independent of dosing or schedule, indicates that IL-2 may not be an ideal option as an adjuvant." (PMID 36510217, 2022). "The much higher level of exosomes needed to silence the IL-2 production from T-cells cultured under unidirectional flow, compared to static conditions, denotes the importance of the culturing conditions and the hydrodynamic environment, on the interactions between CD8+ T-cells and cancer exosomes." (PMID 35323230, 2022). "Thus, IL-2, IL-4, and IL-12 are not very effective when used alone in peptide-based cancer vaccines." (PMID 35967400, 2022). "A Study have shown that andrographolide can promote the production of IL-2 and lymphocytes, and IL-2 activates the cytotoxic activity of NK cells, CD8 + T cells and lymphokine-induced killer cells, and produces TNF-α, which increases the cytotoxicity of lymphocytes to cancer cells." (PMID 36238575, 2022). "Furthermore, synbiotic consumption can prevent an increased secretion of IL-2 by PBMCs in the polyp group without showing any effect in the cancer group." (PMID 35910609, 2022). "Systemic delivery of IL-2, is known to expand T cells while maintaining functional activity, has achieved durable regression in some metastatic melanoma and renal cancer patients, is approved by the FDA, and is used in both CAR-T and TCR-T immunotherapy of cancers today." (PMID 35432319, 2022). "Notably, increased levels of IL-2, TNF-α, IFN-γ, and IL-6 were demonstrated in the memory subsets, indicating that IL-7 possesses the capability to stimulate the memory immune responses against cancers." (PMID 36389666, 2022). "Thus, CARs providing a strong activating signal as it is known for Cetuximab-based CARs, appear not to benefit from additional IL-2 supply in cancers with a suppressive TME." (PMID 35836798, 2022). "IL-15 proves to be a promising candidate for cancer immunotherapy due to its functional similarity to IL-2 with several added benefits, including the lack of stimulation on regulatory T cell populations, reduced activation-induced cell death (AICD), and lower toxicity." (PMID 35806311, 2022). "However, IL-2, IL-4, and IL-12 are not very effective when used alone in peptide-based cancer vaccines." (PMID 35967400, 2022). "With the same cytokine receptor γ chain, IL-2 and IL-4 together regulate cell differentiation, promote the formation of immune cells, improve the killing activity of cytotoxic T lymphocyte (CTL) and NK cells, and play an important role in inflammation and cancers." (PMID 34712741, 2021). "Additionally, unlike IL-2, IL-15 does not significantly affect the numbers and function of regulatory T (Treg) cells, which are stimulated by various cancers to induce suppression of CD8+ T cells and NK cells." (PMID 33537030, 2020).
cancer (continued). "Accordingly, increased IL-2 secretion may stimulate T cell proliferation and IFN-γ production, which in turn can improve the immune response by enhancing cellular immunity against cancer and pathogen-infected cells." (PMID 33266362, 2020). "Subsequently, we investigated whether IL-2/IL-12/IL-18-pre-exposed γδ T cells in the absence of a TCR signal can drive cancer cells into senescence and terminal growth arrest, over time resulting in reduced impedances compared to control." (PMID 31947966, 2020). "Therapeutic delivery of IL-2, such as by systemic IL-2C treatment using the S4B6 clone and 1–2 μg of recombinant IL-2 has seen increasing use in experimental models to modulate CD8 T cell and NK cell populations in vivo to improve responses against pathogens and cancers." (PMID 31412088, 2019). "In general, trials with high-dose systemic IL-2 to support circulating LAK or NK cells were limited by severe and potentially lethal toxicities (e.g., vascular leak syndrome, oliguria, hypotension, myocardial infarction), counterbalancing the beneficial anti-cancer effects of LAK activity." (PMID 26029215, 2015). "The reported data showed that IL-2 might have a negative effect on the specific immune response induced by the relevant mutant ras vaccine in patients with advanced cancer." (PMID 24565030, 2014). "Although the management of patients receiving IL-2 is complex, scheduling and administering cancer therapy in the ICU often strains scarce hospital resources, the patient’s care is transferred to a team that does not have extensive experience with cancer patients or specifically with IL-2." (PMID 24855563, 2014). "It has been applied to the early diagnosis of cancer markers and infectious diseases such as prostate-specific antigen (PSA), human chorionic gonadotropin and α-fetoprotein, amyloid-ß-derived diffusible ligand, interleukin-2, Hantaan viral nucleocapsid protein and HIV-1 p24 antigen." (PMID 22935171, 2012). "Given the clinical development and availability of OX40 agonists and IL-2, it will be of great interest to translate these findings into the clinic and evaluate the therapeutic efficacy of combined anti-OX40/IL-2 therapy for the treatment of patients with cancer." (PMID 22496812, 2012). "Inactivation of mTOR may lead to downregulation of IL-2, thus conferring a direct negative effect in T cell proliferation as well as cancer cell proliferation." (PMID 21318181, 2010). "Thus, changes of co-expression of these shared neighbours with either IL2 or IL6 might disrupt the Jak-STAT signalling pathway and contribute to the progression of cancer." (PMID 21059271, 2010). "The antibody-mediated targeted delivery of pro-inflammatory cytokines (such as IL-2, IL-12, TNF and interferon (IFN) γ) has resulted in impressive increase in the therapeutic index of these biopharmaceuticals, with striking curative activities in animal models of cancer." (PMID 17261171, 2007). "IL-12 reached amaximum in CIN II and decreased in CIN III and carcinoma; but the differencesbetween groups were statistically not significant (K. W. test: P=.068 for IL-12 + p40,P=.264 for IFNγ, P=.077 for TNFα and P=.071 for IL-2)." (PMID 18288269, 2007). "However, a direct influence of IL-2 on cancer cells has not been reported yet." (PMID 41150778, 2025). "In addition, we show that the treatment of TPR/IL2-expanded PBMCs with EpCAM-ReTARGTPRIFNαR149A in the absence of cancer cells promotes T-cell viability and persistence and increases the number of viable T cells from 4 × 105 up to 6 × 105 cells/mL compared to treatment with EpCAM-ReTARGTPR." (PMID 40243928, 2025). "However, HD IL-2 treatment has been associated with significant toxicity, such as the potentially lethal Vascular Leak Syndrome (VLS), and did not significantly improve overall survival in cancer patients." (PMID 36911698, 2023).